EPHA2 (EPH receptor A2)
Diseases named in the same sentence as EPHA2 in open-access papers (continued):
Sharing a sentence is not in itself a finding about the gene and the disease.
EPHA2 also shares sentences with these, for which no sentence is quoted: rhabdomyosarcoma (6 papers); autosomal dominant cataract (4); Kaposi's sarcoma (4); myeloma (4); infectious disease (3); brain cancer (2); CNS tumors (2); colorectal (2); colorectal adenocarcinoma (2); embryonal rhabdomyosarcoma (2); heart failure (2); hematologic malignancies (2); metastatic melanoma (2); -dependent (1); acute lymphoblastic leukaemia (1); acute myocardial infarction (1); adenovirus infection (1); airway hyperresponsiveness (1); alveolar rhabdomyosarcoma (1); amelanotic melanoma (1); Anophthalmia (1); Anterior polar cataract (1); autoimmune polyendocrine syndrome type 1 (1); Bardet-Biedl syndrome (1); benign prostate hyperplasia (1); benign prostate tumor (1); biliary tract cancer (1); brain injury (1); cannabis dependence (1); cervical intraepithelial neoplasia (1).
A further 59 diseases each share a sentence with EPHA2 in 1 paper.